INS (insulin)
Diseases named in the same sentence as INS in open-access papers (continued):
Sharing a sentence is not in itself a finding about the gene and the disease.
diabetes (continued). "It should be noted that some of the nutraceuticals discussed here may aid diabetes prevention not only through direct effects on beta cells, but also by improving peripheral insulin sensitivity or by aiding postprandial glycemic control, thereby mitigating episodes of glucolipotoxicity." (PMID 35052168, 2021). "Furthermore, high salt intake estimated from urine was related to obesity after adjusting for sex, age, insulin treatment, exercise, smoking, alcohol, diabetes duration, HbA1c, and energy intake (adjusted OR: 1.31 (95% CI: 1.10–1.56), p = 0.003), which is the same as the results of previous studies." (PMID 34578892, 2021). "In human clinical trials, injection of bone marrow-derived MSCs to patients with diabetes, specifically those with type 2 diabetes mellitus, improved the function of β cells, reduced the incidence of diabetic complications, and even led to insulin independence in some patients." (PMID 33661932, 2021). "Indeed, patients with diabetes are characterized by not only a compromised insulin secretion and action but also paradoxically elevated plasma concentrations of glucagon that fail to decline appropriately or even increase in response to an oral glucose tolerance test (OGTT)." (PMID 33270148, 2021). "Age >35 years, pre-pregnancy BMI >30, family history of diabetes, previous GDM, altered fasting plasma glucose (FPG), hypothyroidism, and assisted reproductive technologies (ART) were identified as maternal variables significantly associated with the need of insulin therapy." (PMID 33767671, 2021). "Diabetes mellites (DM) is a set of metabolic disorders arising from defective insulin secretion and/or action in which hyperglycemia (HG) is a common feature." (PMID 34408653, 2021). ", diabetes duration of 20 ± 10 years) underwent two 20-day periods of unrestricted living, comparing the Cambridge fully closed-loop system using faster insulin aspart (‘closed-loop’) with standard insulin therapy and a masked continuous glucose monitor (‘control’) in random order." (PMID 34349267, 2021). "Additionally, it prevents diabetes mellitus and hyperglycemia by protecting pancreatic β cells and promoting insulin secretion, alleviating insulin resistance, inhibiting carbohydrate-hydrolyzing enzymes, promoting glucose uptake, and improving gut microbiota dysbiosis." (PMID 34564163, 2021). "Besides promoting glucose uptake, insulin plays an important role in intracellular metabolism, which includes suppressing gluconeogenesis that becomes hampered in insulin-resistant states, such as pre-diabetes and T2D." (PMID 34071774, 2021). "Excluding statin users and individuals with diabetes strengthened the associations with glucose, HbA1c, insulin, and HOMA-IR, which could not be explained by physical activity, BMI, and waist circumference." (PMID 34886380, 2021). "Moreover, patients with atrial fibrillation and insulin-requiring diabetes had an increased thromboembolic risk (stroke/systemic embolism) at 1 year compared to those patients with diabetes but without insulin therapy." (PMID 34746266, 2021). "Thus, DS20060511 may act as an antidiabetic agent with an entirely novel mechanism of action in patients with impaired actions of insulin in the skeletal muscle and those with either type 1 or 2 diabetes receiving insulin and/or exercise therapy." (PMID 34417555, 2021). "In addition, whether CF patients diagnosed with pre-diabetes could benefit from ‘early’ initiation of insulin therapy it is still debated." (PMID 34017312, 2021). "On the other hand, a review of literature data performed in 2004, including diabetes as well as metabolic syndrome patients, suggested the inability of ω-3 PUFAs to have a direct outcome on fasting plasma glucose, insulin level, glycosylated hemoglobin (HbA1C) levels or insulin sensitivity." (PMID 34926582, 2021).
diabetes (continued). "Therefore, our results reveal an endocrine/paracrine role of endothelial cells in regulating insulin sensitivity, which may have therapeutic implications in treating diabetes and insulin resistance through manipulating vascular endothelium." (PMID 34489478, 2021). "The characteristics of SGLT2i, and especially GLP1-RA, due to its hypoglycaemic potency, may permit a de-escalation of insulin, or even a withdrawal, in the case of a preserved insulin reserve and if only a few years have passed since the time of a diabetes diagnosis." (PMID 34070103, 2021). "Diabetes mellitus (DM) is a chronic metabolic disorder with insufficient insulin production or insulin resistance, resulting in a high level of blood glucose." (PMID 34744728, 2021). "Patients with diabetes have been recommended to follow general guidelines on infection risk reduction, blood glucose monitoring, taking medication, injecting insulin and noninsulin drugs adequately, and maintaining a healthy lifestyle (through diet and physical activity)." (PMID 33769945, 2021). "SARS-CoV-2 infection may not only worsen the preexisting diabetes but also cause new cases of diabetes in non-diabetic subjects through a direct pancreatic damage and a resultant impairment of insulin secretion from β-cells." (PMID 34690930, 2021). "It was reported that the oral administration of date seed extract combined with insulin had an antihyperglycemic effect as compared to seed extract alone in streptozocin diabetic rats, and could minimize the toxic effects of diabetes on the liver and kidney for diabetic rats." (PMID 33572627, 2021). "Diabetes mellitus may increase suicidality through multiple mechanisms—the accumulation of diabetes related complications and disabilities, the occurrence of adverse events, stress, and easy access to potentially lethal means (e.g., insulin)." (PMID 33924079, 2021). "Insulin therapy is an essential component of medications used in DM treatment and the cornerstone of treatment in type 1 and type 2 diabetes." (PMID 33556090, 2021). "It suggests that insulin use alone might not be associated with hypertension, but depends on the duration of diabetes as well." (PMID 34424924, 2021). "We assess sex-dimorphic (73,089/50,404 women and 67,506/47,806 men) and sex-combined (151,188/105,056 individuals) fasting glucose/fasting insulin genetic effects via genome-wide association study meta-analyses in individuals of European descent without diabetes." (PMID 33402679, 2021). "Similarly, the NICE guidelines state that continuing subcutaneous basal insulin in a child or young person who was using a basal insulin before DKA may be continued in discussion with a diabetes specialist." (PMID 34151029, 2021). "However, B6-ob/ob mice, which carry a mutation in the Leptin gene, become obese and insulin-resistant without developing diabetes, and therefore serve as non-diabetic controls." (PMID 34445304, 2021). "Over the past decade, the rise of diabetes technologies, including dosing advisors, continuous glucose monitoring systems, insulin pumps and automated insulin delivery systems has led to great improvements in the therapies available particularly to those requiring insulin." (PMID 33950566, 2021). "Although continuous follow-up of our diabetes cohort for up to 17 years supported that the use of insulin is independently predictive for all-cancer death, we were not able to show any association between insulin use and GCa death or GCa risk." (PMID 34356646, 2021). "On the other hand, it is hypothesized that the worse outcomes of COVID-19 patients with diabetes mellitus are attributable to the angiotensin-converting enzyme-2 receptor-mediated entry of the virus in the host cell, which damages the insulin-producing pancreatic islet cells." (PMID 34940517, 2021). "Diabetes mellitus (DM) is a chronic disease that appears when the pancreas is unable to produce enough insulin, or the body cannot use this hormone properly." (PMID 34943023, 2021).
diabetes (continued). "Thus, the evidence on effectiveness and safety of insulin in patients with diabetes is a priority." (PMID 34876671, 2021). "Diabetes mellitus (DM) is a common metabolic disease manifesting as defects in insulin secretion, insulin action or both, which results in a type of hyperglycemic status." (PMID 34957219, 2021). "Furthermore, patients with adult diabetes may present with abnormalities in white matter content that correlate with cognitive function, suggesting a potential link between blood insulin and white matter structure." (PMID 33669242, 2021). "A validated insulin adherence questionnaire for diabetes mellitus (DM) was used to assess insulin adherence." (PMID 35002492, 2021). "Diabetes mellitus (DM) is one of the most common chronic-degenerative diseases in the adult populations; type 1 is characterized by the inability to produce the typical amounts of insulin and type 2 diabetes is identified by the body’s reduced sensitivity to insulin." (PMID 35072165, 2021). "Thus, increased insulin signalling in early diabetes, prior to the development of glomerular insulin resistance, may suppress FoxO1 activity and IGFBP-1 expression in the glomerulus and associated signalling." (PMID 33758952, 2021). "However, it is difficult for most persons with diabetes to fully integrate the complex interplay between the duration of the suspension, remaining insulin on board, and glucose rate of change, as well as any exercise-related factors, to estimate the CHO amount required for treatment of hypoglycemia." (PMID 33535013, 2021). "Diabetes mellitus (DM) is a group of metabolic diseases characterised by hyperglycaemia resulting from defects in insulin secretion, insulin action (or both) and is one of the most commonly encountered endocrinopathies worldwide." (PMID 34072110, 2021). "Further research measuring glycemia and insulin dynamics beyond TB treatment is ultimately needed to determine if the post-TB DM phenotype is more akin to gestational diabetes or if those patients carry a different risk of developing relapse of TB disease." (PMID 34813631, 2021). "Indeed,many recalled the cumbersome process of having to “untangle yourself”(Participant#1) or “fumble about in your pocket” (Participant#3) to retrievetheir pump to manage diabetes using the previous system, whereas the app enabledthem to check glucose levels and administer insulin effortlessly." (PMID 34261348, 2021). "In order to avoid conflict due to the fact that fasting glucose and insulin levels are strongly correlated to diabetes diagnosis, we built two independent statistical models featuring, respectively, fasting glucose and fasting insulin in Model A and diabetes prevalence in Model B." (PMID 35047582, 2021). "Following the classification schemes used in human medicine, diabetic cats generally suffer from a type 2-like diabetes mellitus that may be phenotypically characterized by a combination of impaired insulin action in liver, muscle, and adipose tissue (insulin resistance), and beta-cell failure." (PMID 34046446, 2021). "Interestingly, the c-peptide plays a role in the tuning of insulin signaling and in endothelial physiology, which could account for the microvascular dysfunction observed in diabetes." (PMID 34054596, 2021). "Diabetes mellitus (DM) is a pathological condition characterized by a high blood glucose (hyperglycemia) and insulin concentration for a long period of time." (PMID 34804554, 2021). "In addition, in patients with unknown diabetes and hyperglycemia, when acute myocardial infarction occurs, even if blood glucose was significantly elevated, insulin therapy was rarely used." (PMID 34912898, 2021). "Moreover, reduced levels of ACE2 (all isoforms) were shown to be associated with acute respiratory distress syndrome and with decreased insulin secretion in diabetes progression, which is in agreement with our results in CF patients with pancreatic insufficiency." (PMID 33401565, 2021).
diabetes (continued). "Consequently, restoration of endogenous insulin secretion represents a vital step in preventing hyperglycemia and hypoglycemia and to minimize the pathological complications of diabetes and self-management of glycemia; however, protection against inflammatory infections is most important." (PMID 33661932, 2021). "However, studies dealing with patients with diabetes who self-inject insulin suggest no increased risk of infection when doses are given without skin preparation." (PMID 33418557, 2021). "As unhealthy diets and a lack of physical activity also contribute to a global rise in the prevalence of obesity and both type 1 and II diabetes, a lifestyle change could be a good companion to insulin-signaling targeted therapy in reducing hyperglycemia and associated diabetes." (PMID 34203830, 2021). "A recent study has shown better clinical outcomes in patients on metformin compared with those on insulin, but again we should consider that the use of insulin may just indicate that the diabetes was more severe and should be interpreted as a potential confounder." (PMID 33648564, 2021). "However, it should be noted that statin use may increase fasting blood glucose and HbA1c levels due to increased insulin resistance or reduce insulin release, which could contribute to the genesis of diabetes." (PMID 33714276, 2021). "Mix-up of the insulin pens/cartridges such as choosing the wrong pen/cartridge when using both long- and short-acting insulin is not uncommon and is a potential risk for individuals with diabetes due to adverse consequences associated with incorrect insulin usage." (PMID 34924015, 2021). "Therefore, a better therapeutic strategy would be to enhance β cell mass and restore insulin secretory capacity, which might cure different types of diabetes." (PMID 34882233, 2021). "Furthermore, alginates may reduce cholesterol and prevent diabetes, especially by avoiding postprandial peaks of glucose and insulin, and delaying the gastric transit." (PMID 33917044, 2021). "Indeed, peripheral demyelination is a common diabetes-induced complication, and insulin signaling may contribute to myelin production in Schwann cells." (PMID 33669242, 2021). "Thus, three subtypes of diabetes may exist, wherein the initial defect resides in each component of insulin homeostasis (resistance, secretion, clearance)." (PMID 34206745, 2021). "However, in this study relatively low doses of insulin were used, while in a real-life setting, insulin therapy is usually initiated in patients with longer-lasting diabetes, worse metabolic control and in older age compared to patients treated with other therapeutic regimens." (PMID 33562380, 2021). "Consistent with the heterogenous nature of the etiology of diabetes, these treatments elicit their therapeutic effects via modulation of different metabolic pathways such as insulin sensitivity, renal glucose reabsorption, glucose-dependent insulin secretion, and hepatic glucose production." (PMID 34822370, 2021). "Likewise, Penesova and colleagues showed that salsalate administration in obese subjects without diabetes resulted in increased insulin levels associated with lower insulin clearance and unaltered insulin secretion." (PMID 33668109, 2021). "Furthermore, boosting fiber intake and/or limiting sugar intake improves the health of captive animals by variably reducing obesity, diabetes, cataracts, fatty liver, parasite burden, and serum insulin and cholesterol, while improving body and coat conditions in Javan slow loris." (PMID 34950117, 2021). "Thus, our results further support the hypothesis that the action of insulin in the brain goes beyond glycaemic control and diabetes-related changes in the brain." (PMID 33597002, 2021).
diabetes (continued). "Although it remains unclear as to what initiates DCM on the molecular level, the major clinical and biochemical abnormalities in diabetes, such as hyperglycemia, systemic insulin resistance, and impaired cardiac insulin signaling, are the risk factors contributing to the pathogenesis of DCM." (PMID 33397369, 2021). "Diabetes mellitus (DM) is a group of metabolic disorders characterized by increased blood glucose due to insufficient insulin amount or defective insulin action or both." (PMID 34575638, 2021). "Diabetes is caused by either lack of insulin production by the pancreas (type 1 diabetes, T1D), when the amount of insulin produced by the pancreas is insufficient to carry out all blood glucose regulation processes, or by decreased insulin sensitivity by the body cells (type 2 diabetes, T2D)." (PMID 33686454, 2021). "Although exclusion of chronic diseases such as pre-existing diabetes mellitus reduces excessive number of confounders, this probably contributed to a small share of effects such as development of cases of gestational diabetes mellitus treated with insulin (GDM-2) or prior GDM." (PMID 33671089, 2021). "Although some studies suggest that fasting may be helpful for people with diabetes in improving insulin sensitivity and glucose control along with modest decreases in body weight, the American Diabetes Association does not recommend fasting as a technique for diabetes management." (PMID 34067055, 2021). "Moreover, insulin therapy may increase in-hospital admission in patients with COVID-19 and diabetes (OR=1.31; 95% CI, 1.06-1.61)." (PMID 34367067, 2021). "For feline DM, two recent GWAS analysis in this breed identified several candidate genes, as well as genomic regions involved in lipid metabolism, insulin sensitivity and Beta-cell dysfunction as likely to be associated with diabetes mellitus in this breed." (PMID 34874954, 2021). "Furthermore, an interesting study conducted in mice that become identifiably obese due to homozygous diabetes spontaneous mutation (Leprdb) showed that CGA treatment inhibited G6Pase expression, improved lipid metabolism, insulin sensitivity, and glucose tolerance via AMPK activation." (PMID 34371900, 2021). "Finally, CRP was included among the covariates that masked the association of the insulin sensitivity index or fasting insulin concentration with all-cause mortality in older adults without diabetes." (PMID 33715620, 2021). "Whether by improving the response or increasing insulin secretion, the association between low VITD levels and dysglycemia is the goal of studies aiming at a better understanding of the pathogenesis of diabetes, with supplementation of this vitamin being considered as a potential adjunctive therapy." (PMID 34578857, 2021). "We concluded that, prolonged pulsatile versus continuous intravenous insulin resulted in a significant increase in hypoglycemic effects and insulin sensitivity in T1D with diabetes duration up to 10 years the differential effect of PI was dependent on duration of diabetes." (PMID 34335462, 2021). "Gestational diabetes and diabetes mellitus reported the most common health condition in our population with 24.6%, as it also showed no significance whatsoever alongside with the number of past CSs due to the fact most of them had their disease under control either by diet or insulin." (PMID 33633880, 2021). "The 2021 American Diabetes Association Standards of Medical Care also did not provide specific starting insulin dosages, although increasing prandial and supplemental insulin in addition to basal insulin in higher doses of GC was suggested." (PMID 34529703, 2021). "Mifepristone, a glucocorticoid and progesterone receptor antagonist, has been shown to improve insulin sensitivity and decrease fasting plasma glucose concentrations and HbA1c concentrations in patients with Cushing’s disease and impaired glucose tolerance or diabetes mellitus." (PMID 33995272, 2021).